ACE (angiotensin I converting enzyme)
Diseases named in the same sentence as ACE in open-access papers (continued):
Sharing a sentence is not in itself a finding about the gene and the disease.
COVID-19 (continued). "Thus, several authors hypothesize that a down-modulation of ACE2 tissue activity-due to its shedding or internalization into the cells along with the virus—and the subsequent ACE/ACE2 imbalance could substantially contribute to the genesis of the hyperinflammatory state seen in COVID-19." (PMID 34359922, 2021). "In the present study, the BIOiSIM was used for the computational prediction of ACE inhibitor and CCB drug dispositions in the context of tissues related to COVID-19 pathogenesis." (PMID 33805419, 2021). "Therefore, some researchers speculated that ACE2 was possibly related to the severity of patients with COVID-19, and even a hypothesis of using inhibitors that block both ACE and ACE2 zinc metalloproteases and their downstream pathways in these patients was proposed." (PMID 34631727, 2021). "Our identified ACE and REN inhibitor captopril and AGTR1 targeting losartan are potential anti-COVID-19 drugs." (PMID 34067609, 2021). "Here, we present ACE, a paralog of ACE2, which also plays an important role in the treatment of COVID-19." (PMID 35095487, 2021). "Use of ACE inhibitors and ARB (Angiotensin II receptor blockers) in COVID-19 patients is being debated since the start of this pandemic." (PMID 34122129, 2021). "Expression of CD143 (angioconverting enzyme, ACE) was increased in monocyte subpopulations, cDC2, DC3, and tDCs in COVID-19 patients compared to healthy controls, especially at early time points." (PMID 34614036, 2021). "In most cases these patients are treated with anti-hypertensive drugs including ACE inhibitors or ANGII receptor blockers; consistently, prescription of anti-hypertensives was more frequent among patients with COVID-19." (PMID 33435929, 2021). "It does not mean that this problem is unequivocally resolved and not requires further basic research and clinical observations on the effects of ACE inhibitors and AT1R blockers (and other drugs, e.g., statins) in patients infected with SARS-CoV2 and COVID-19." (PMID 33925881, 2021). "We also found ACE/CD143 to be upregulated at early timepoints in monocytes and DC3 of COVID-19 patients correlating with markers of inflammation." (PMID 34614036, 2021). "Quinapril is an angiotensin converting enzyme (ACE) inhibitor and the ACE inhibitors have been suggested to be beneficial for COVID-19 patients." (PMID 33841751, 2021). "Furthermore, since African descent have a lower response to ACE inhibitors compared to calcium blockers and β-adrenergic blocker anti-hypertensives, this decreased response could potentially contribute to the low COVID-19 prevalence and fatality in Africa." (PMID 33901167, 2021). "These factors implicate a potentially complex interplay between tissue ACE/ACE2 expression and circulating ACE/ACE2 activity in contexts of both cardiovascular disease and COVID-19." (PMID 34359878, 2021). "This difference has been demonstrated by the debates related to ACE inhibitors where concerns were raised over its use given the possibility of increasing ACE2 expression although subsequent evidence suggests that ACE inhibitors do not appear to increase the risk of COVID-19." (PMID 33757497, 2021). "However, serum ACE activity could not serve as an independent risk factor for the severity of COVID-19." (PMID 33238910, 2020). "The use of ACE inhibitors and ARB in patients with COVID-19 has been called into question by some, due to the evidence that SARS-CoV-2 uses the ACE2 receptor for entry into target cells." (PMID 33195473, 2020). "For example using different ACE inhibitors or ARBs may cause upregulation of ACE2 receptors and it is well established that ACE2 is a functional receptor used for entry of the COVID-19 to the cell, and it is supposed that this upregulation worsens the impact of infection." (PMID 33117174, 2020).
COVID-19 (continued). "This is the first study assessing the safety of CVD medications, and in particular ACE inhibitors and ARB studied separately, in a nation-wide representative sample of COVID-19 inpatients, mostly aged >65." (PMID 33195473, 2020). "As the SARS-CoV-2 pulmonary invasion is mediated through the ACE2 receptor, theoretical concerns about the ongoing angiotensin converting enzyme (ACE) inhibitors and angiotensin II receptor blockers (ARB) over the COVID-19 prognosis were raised." (PMID 32748880, 2020). "Angiotensin-converting enzyme (ACE) 2, an important receptor in the pathogenesis of COVID-19, was demonstrated to be expressed in the thyroid tissues." (PMID 33117282, 2020). "Literature experimental results identified angiotensin-converting enzyme ACE and Spike proteins particularly involved in COVID-19." (PMID 33363465, 2020). "Angiotensin-converting enzyme (ACE) inhibitor and angiotensin-receptor blocker (ARB) have been hypothetically suggested to exacerbate COVID-19 due to increase in angiotensin II level." (PMID 32483488, 2020). "While the effects of ACEi/ARBs and soluble ACE2 in COVID-19 are not fully known, ACE2 is an endogenous inhibitor of the ACE/Ang II/AT1R pathway and the downstream vasoconstrictive, inflammatory, prothrombotic, and fibrotic responses." (PMID 32922297, 2020). "In patients with COVID-19, there is no consistent change in circulating ACE and ACE2 activity and in plasma concentrations of ANGII and Ang1-7 in mild-to-serious infection." (PMID 40631549, 2025). "Considering that ACE and ACE2 are homologues, the role and mechanism of ACE2 in COVID-19 may be an area for further exploration." (PMID 40160824, 2025). "One of these pathways is the renin–angiotensin system (RAS) signaling pathway via suppression of the angiotensin I-converting enzyme (ACE), which may help COVID-19 patients experience less tissue damage." (PMID 41567862, 2025). "ACE activity is reduced in patients with COVID-19 ARDS compared to non-COVID-19 ARDS especially in finally non-surviving patients, and in patients with severe versus non-severe COVID-19." (PMID 39821855, 2025). "In this prospective study we used liquid chromatography-tandem mass spectrometry (LC-MSMS) to quantify equilibrium peptide levels (Ang I-IV, Ang 1–7, Ang 1–5) (RAS fingerprint) and active ACE and ACE2 in order to identify their implications for prognosis in COVID-19 patients." (PMID 39821855, 2025). "Indeed, we have demonstrated that sub-acute exposure to PM2.5 altered the ACE/ACE2 system, with possible consequences for COVID-19 pathogenesis." (PMID 39195662, 2024). "In an attempt to establish whether some demographic or clinical factors could affect ACE and ACE2 activities or AngII and Agn1-7 concentrations in COVID-19 patients, we performed univariable and multivariable linear regression analyses." (PMID 38543635, 2024). "ACE is known as a functional receptor of SARS viruses including SARS-no-CoV2, and the severity of COVID-19 has been associated with the levels of ACE2 and TMPRSS2 co-expression and the proteinase activity of FURIN." (PMID 39273283, 2024). "This study highlights the lack of significant changes in key RAS components during COVID-19 in a clinical cohort and provides critical in vitro evidence supporting the continued use of ACE inhibitors and ARBs in treating patients." (PMID 40417281, 2024). "This metabolite is a peptide involved in the inhibition of the angiotensin-converting enzyme (ACE), which might explain some cardiovascular changes in long COVID-19 patients." (PMID 39590834, 2024). "Regardless of the paucity of accessible data, a few observational studies have failed to establish a relation between the seriousness of COVID-19 and the usage of ACE inhibitors and ARBs." (PMID 39337343, 2024). "Surprisingly, we found that earlier use of ACE inhibitors (ACEi) or ARBs had no significant influence on the occurrence of AKI in patients with COVID-19." (PMID 38715992, 2024).
COVID-19 (continued). "Additionally, COVID-19 enters the cells through the angiotensin-converting enzyme 2 (ACE2) receptor, leading to rising levels of bradykinin and decreasing ACE levels." (PMID 39502969, 2024). "Decreased ACE2 bioavailability and increased ACE activity level can increase the activity of Angiotensin-II (AngII) in RAS and may lead to COVID-19-induced inflammation and lung injury." (PMID 37667339, 2023). "Based on these assumptions, here we examine, in a mouse model, the effects of PM2.5 exposures on ACE, ACE2, COX-2, HO-1, and iNOS in the main organs involved in COVID-19 pathology (lung, heart, liver, and brain), to test the potential close relationship between PM2.5 exposure and disease severity." (PMID 36901403, 2023). "Distribution of ACE-1 (rs4343), TMPRSS2 (rs12329760) and ACE-2 (rs908004) Alleles among severe and non-severe COVID-19 patients." (PMID 37426824, 2023). "We also evaluated if the serum ACE activity level was related to available demographic characteristics and/or clinical parameters in the post-COVID-19 and non-COVID-19 groups." (PMID 37108839, 2023). "In the results of this study, the genotypic profiles of ACE and ACE2, individually, did not represent susceptibility or protection for the patient affected by COVID-19." (PMID 38032879, 2023). "In earlier studies, we noticed significantly reduced carboxypeptidase N (CPN, KKS member) activity and excessive angiotensin-converting enzyme (ACE, RAS member) activity in the sera of both hospitalized COVID-19 patients and a subgroup of convalescent patients." (PMID 37511837, 2023). "This is because SARS-CoV-2 infection causes angiotensin-converting enzyme (ACE) and its homolog angiotensin-converting enzyme 2 (ACE/ACE2) balance disruption and renin-angiotensin-aldosterone system (RAAS) activation, which ultimately leads to COVID-19 progression." (PMID 37748553, 2023). "They measured ACE levels both on admission and in the follow-up of the patients, showing that ACE level was increased in the follow-up in comparison to that in active infection, but ACE2 level decreased during the resolution of COVID-19." (PMID 37432962, 2023). "The serum ACE activity was assessed in available samples from patients of the three subgroups (COVID-19, post-COVID-19, and non-COVID-19)." (PMID 37108839, 2023). "Imbalances in the RAS, characterized by increased ACE activity and reduced ACE2 activity, could contribute to inflammation, vasoconstriction, oxidative stress and tissue damage observed in severe COVID-19 cases." (PMID 37511837, 2023). "Baseline serum ACE activity of severe and non-severe COVID-19 patients was reduced compared to normal controls, with the lowest levels seen in the severe COVID-19 group." (PMID 37175942, 2023). "Although there were initial concerns regarding the usage of ACE inhibitor as drugs for treating COVID-19 patients, there is currently no scientific evidence which suggests it is potentially harmful to administered patients." (PMID 36757984, 2023). "Observational studies have also shown that chronic treatment with ACE inhibitors or ARBs is not harmful and can be beneficial in COVID-19 patients." (PMID 36983871, 2023). "If this second hypothesis is correct, drugs such as ACE-inhibitors, which inhibit the RAAS, could be protective in COVID-19." (PMID 35162972, 2022). "Thus, the race for ACE is a search for drugs that could target both the RAAS and kallikrein-bradykinin system in order to reconstitute the balance within these closely linked pathways, thereby subsequently fighting successfully COVID-19 and thereby potentially preventing long COVID-19." (PMID 35685188, 2022). "A prospective cohort study also found that ACE inhibitors and AT1R blockers are associated with a reduced progression of COVID-19 and do not increase the risk of intensive care." (PMID 34973134, 2022).
COVID-19 (continued). "It appears from the present results that more enzymes than ACE and CPN may be involved in COVID-19, but they must be metalloproteases, because all activity was suppressed by EDTA." (PMID 35330406, 2022). "In a large observational study in England, the use of ACE inhibitors and ARBs did not increase the risk of intensive care unit (ICU) admittance, while significantly reducing the risk of COVID-19 among over 8 million participants." (PMID 35453563, 2022). "The systemic activity of ACE, estimated by the angiotensin-II-to-angiotensin-I ratio (ACE-S), was markedly lower with severe versus non-severe COVID-19 (1.6 vs. 2.6), suggesting decreased functional ACE activity." (PMID 36418458, 2022). "ACE-1 is a regulator of BK, making it feasible that inhibition of ACE-1 could aggravate the ARDS condition in COVID-19 patients by increasing the levels of active BK." (PMID 35350780, 2022). "In a retrospective study, however, there was no connection among severe COVID-19 outcomes and chronic ACE inhibitor/Angiotensin II receptor blocker medication." (PMID 36363511, 2022). "In this study, the serum activity of ACE and CPN in sera of hospitalized COVID-19 patients (HoP) was investigated using a specific NRA based on the neuropeptide BK, which is a potent vasodilator, mild diuretic, pro-inflammatory agent and involved in the mechanism of pain." (PMID 35330406, 2022). "We sought to identify disruptions of the classical (ACE)/angiotensin (Ang) II/Ang II type-1 receptor (AT1R) and the counter-regulatory ACE2/Ang 1-7/Mas Receptor (MasR) pathways in patients with COVID-19 and correlate these with severity of infection and markers of inflammation and coagulation." (PMID 35913134, 2022). "Some genes that may be related to severe COVID-19 pathophysiology and are good candidates for experimental investigation include PRKG1, ACE, CFB, CRP, CTNNB1, EGFR, and VEGFA." (PMID 35794133, 2022). "This could be due to use of ACE inhibitors, as they indirectly increase cellular ACE2 receptors which could be a receptor for COVID-19." (PMID 35722221, 2022). "In another investigation, there was no indication of increased severity of COVID-19 illness in London patients receiving chronic ACE inhibitor or Angiotensin II receptor blocker therapy." (PMID 36363511, 2022). "Our results are supported by other observational studies of these drug classes and endorse the position statement of the European Society of Cardiology that treatment with ACE inhibitors should not be discontinued in patients with COVID-19." (PMID 35837356, 2022). "We explored potential factors contributing to the reduced intrinsic ACE activity in severe COVID-19 with and without use of RAS inhibitors." (PMID 36418458, 2022). "Recent meta-analyses conclude that both the use of ACE inhibitors and ARBs are safe and do not increase the risk of SARS-CoV-2 infection, nor does it increase the severity of COVID-19 (need for intensive therapy, use of mechanical ventilation, and death)." (PMID 36187294, 2022). "We compared the prevalence of ACE rs4646994, AGT rs699, and AGTR1 rs5186 polymorphisms between severe and non-severe cases of COVID-19." (PMID 34805533, 2021). "Further studies should be conducted to investigate whether this imbalance between ACE/ACE2 may promote and accelerate lung injury in respiratory infections, including coronavirus disease 2019 (COVID-19)." (PMID 34751382, 2021). "The ACE2 polymorphism has been associated with varying degree of disease severity and clinical outcomes of COVID-19, with absence of ACE D/D genotype conferring protection against severe lung injury." (PMID 34834450, 2021). "The same tendency of changes with increased ACE2 and decreased ACE protein levels, paired with increased Ang 1–7 levels, were found in the serum of patients with COVID-19-related and non-COVID ARDS." (PMID 35498160, 2021). "ACE and ACE2 activities were unchanged in patients with COVID-19 in this study." (PMID 35498160, 2021).
COVID-19 (continued). "Considering the dual inhibitory effect of CIB-6 on STAT3 and ACE, CIB-6 could be further explored for development as a new anti-COVID-19 drug." (PMID 33805945, 2021). "Nevertheless, there is not yet clear evidence regarding the clinical impact of ACE inhibitors/ARBs in COVID-19." (PMID 34061779, 2021). "In contrast, stem cells in children and fetal-derived stem cells in pregnant women have a low ACE/ACE2 ratio, exert their immunomodulatory and regenerative functions, inhibit pulmonary edema hypoxia, and make children/pregnant women more tolerant to COVID-19." (PMID 34769218, 2021). "There are as yet no data regarding the impact of restoring the ACE/ACE2 balance in COVID-19 with or without AKI." (PMID 33805760, 2021). "If this same correlation is seen in patients with COVID-19, plasma ACE1 levels (serum ACE) could be used to approximate the activity of ACE2 in COVID-19 positive patients." (PMID 34086837, 2021). "In addition to differences in the activity level and the ACE/ACE2 ratio, other variations among stem cells can be the subject of future investigation for a better understanding of the resistance against COVID-19." (PMID 34769218, 2021). "Recently, a randomized clinical trial was conducted to determine whether ARBs and ACE inhibitors taken by patients with CVD, contributed to the progression of severe COVID-19." (PMID 33498183, 2021). "In view of the central role of ACE-2 receptor in cellular viral entry of SARS-CoV-2, in combination with the importance of the renin-angiotensin-aldosterone-system (RAAS) in maintaining endothelial homeostasis, a putative effect of inhibition of ACE and AT2 on COVID-19 severity has been proposed." (PMID 34054876, 2021). "Especially when the balance between the ACE and ACE2 was disrupted in COVID-19 patients, the increase in Ang II actions could lead to myocardial inflammation, oxidative stress, and myocyte apoptosis." (PMID 33909683, 2021). "In a previous study, baseline serum ACE activity of severe and non-severe COVID-19 patients was decreased compared to normal controls; the lowest levels were noted in the severe group." (PMID 34358119, 2021). "At this time, there is no concrete clinical evidence to support the use of ACE inhibitors or ARBs in COVID-19 treatment." (PMID 34177298, 2021). "In this study, the pulmonary ACE protein expression was diminished in COVID-19-related and non-COVID ARDS." (PMID 35498160, 2021). "This is in line with a case series suggesting that ACE is not a suitable biomarker for differentiating between mild and severe COVID-19." (PMID 34945736, 2021). "Professional societies have now released position statements stating that ACE inhibitors and ARBs should not be withdrawn either as a preventive measure or as a treatment option in COVID-19." (PMID 32685191, 2020). "The main findings of this retrospective, observational study, are the following: first, it is confirmed that, among hypertensive subjects, the use of ACE inhibitors or ARBs up to two years preceding SARS-CoV-2 infection did not affect the severity of COVID-19." (PMID 32579597, 2020). "Due to the fact that SARS-CoV and 2019-nCoV both use ACE2 for cell entry, we can speculate that for COVID-19, ACE2 may also be downregulated by 2019-nCoV binding to ACE2, while the activation of the ACE-Ang II axis will promote lung injury." (PMID 32522846, 2020). "Together these results suggest that an imbalance between ACE/AngII/AT1 and ACE2/Ang1-7/Mas axes toward the activation of the former might play a pathophysiological role in COVID-19." (PMID 32850927, 2020). "Because of the potential harm of discontinuation of ACE inhibitors and ARBs and lack of prospective clinical evidence, the international societies recommend continuing these medications in COVID-19 patients as well as the uninfected ones." (PMID 32851877, 2020).